AHI1 (Abelson helper integration site 1)
Diseases named in the same sentence as AHI1 in open-access papers (continued):
Sharing a sentence is not in itself a finding about the gene and the disease.
depression (12 papers, 2011 to 2025). "Previous studies reported the relationship between AHI1 polymorphism and psychiatric disorders, including schizophrenia, autism spectrum, major depressive disorder and bipolar disorder." (PMID 38036661, 2024). "In this study, we found that Ahi1, a protein associated with susceptibility to depression, regulated serotonin production through the GR/ERβ/TPH2 pathway, indicating a critical role for Ahi1 in the regulation of depression." (PMID 35643536, 2022). "Two of these genes, IFNGR1 and AHI1, both linked to ‘abnormal depression-related behavior’, are predicted to have a novel interaction between them." (PMID 31481665, 2019). "In summary, Ahi1 deficiency contributes to depression-like behaviors together with the decrease of monoamine neurotransmitters and high level of MAO activity." (PMID 24691070, 2014). "Our previous studies showed that Abelson helper integration site-1 (Ahi1) deficiency causes depression-like behaviors in mice." (PMID 24691070, 2014). "Recently, several linkage and association studies have further identified AHI-1 as a susceptibility gene for schizophrenia, a major neuropsychiatric disorders associated with depression." (PMID 22248740, 2011). "In addition, AHI1 has been extensively studied in depression models, where its loss-of-function mutations are linked to depressive behaviors in mice." (PMID 40242760, 2025). "Since depression can be caused by multiple pathogenic pathways, it is important to investigate whether different mechanisms underlie the depressive phenotypes of Ahi1 KO mice." (PMID 24691070, 2014). "The link between AHI1, immune function and MS is particularly interesting considering studies on major depressive disorder (MDD), characterized by an atypical immune response to EBV infection." (PMID 40242760, 2025). "Depression-related arginine vasopressin (AVP) reduces AHI1 expression, which disrupts Tyk2 and interferon signaling, further compromising immune defense." (PMID 40242760, 2025). "Currently, only the analgesic drug meptazinol has been discovered to upregulate AHI1 and Tyk2 expression in a mouse model of depression, suppressing viral infection." (PMID 38916735, 2024). "Studies investigating the immunomodulatory role of AHI1 suggested a link between AHI1 expression and antiviral immune response in major depressive disorder (MDD) patients." (PMID 38036661, 2024). "The in vivo studies indicated the role of AHI1 in mood disorders, showing that the knock-out of Ahi1 resulted in depressive-like behaviour and neurochemical changes in depression-related serotonin and dopamine levels in different brain regions." (PMID 38036661, 2024). "In contrast, ATP treatment for one week significantly improved depression-like behaviors in Ahi1 KO mice but was ineffective in imipramine treatment, suggesting that ATP is a faster-acting antidepressant." (PMID 36691038, 2023). "The results showed that treatment with the classical antidepressant imipramine for 3 weeks significantly improved depression-like behaviors in Ahi1 KO mice." (PMID 36691038, 2023). "In our studies, we found that exercise significantly improved depression-like behaviors and increased mitochondrial Ahi1/GR levels and ATP levels in the hypothalamic tissues of Dex-induced mice." (PMID 36691038, 2023). "In this study, we found that ATP levels decreased and mitochondrial DNA (mtDNA) copy numbers increased in depression-related brain regions in Dex-induced depressive mice and Ahi1 knockout (KO) mice." (PMID 36691038, 2023). "To explore the underlying mechanisms of depression-like behaviors, we measured 5-HT levels by HPLC in hippocampal tissues from male Ahi1 KO mice because previous studies have shown that serotonin is involved in the regulation of depression." (PMID 35643536, 2022). "We previously showed that Ahi1 knockout (KO) mice exhibited depression-like behavior accompanied by a significant decrease in brain serotonin." (PMID 35643536, 2022).
depression (continued). "Our findings revealed the association of decreased cytoplasmic GR levels with a resistance to the antidepressant IM in Ahi1 KO mice, providing the potential mechanism of antidepressant-resilient depression." (PMID 33782379, 2021). "The beneficial effects of PBM on depression have also been demonstrated in a space restriction-induced depression animal model and in Abelson helper integrationsite-1 (Ahi1) KO mice." (PMID 32475349, 2020). "All these findings supported that Ahi1 KO mice are a good depression model for screening therapeutic targets." (PMID 24691070, 2014). "In this study, we characterized the neurochemical changes of Ahi1 KO mice, especially on depression-related monoamine neurotransmitters such as serotonin and dopamine in different brain regions." (PMID 24691070, 2014). "Our findings suggest that Ahi1 KO mice can be used for studying the mechanisms of depression and screening therapeutic targets." (PMID 24691070, 2014). "Our findings suggest that Ahi1 KO mice can provide a genetic mouse model to study the pathogenesis of depression and to identify new therapeutic targets." (PMID 24691070, 2014). "The characterizations of Ahi1 KO mice demonstrated that Ahi1 KO mice is a good genetic model of depression and can be used for studying the mechanism of depression and screening therapeutic targets." (PMID 24691070, 2014). "In line with this, we observed that ATP could rapidly improve depression-like behavior in Ahi1 KO mice compared to imipramine treatment." (PMID 36691038, 2023). "In the present study, western blot, gene knockdown, immunofluorescence, dual-luciferase reporter assay, and rescue assay were used to detect changes in the Ahi1/GR/ERβ/TPH2 pathway in the brains of male stressed mice and male Ahi1 KO mice to explain the pathogenesis of depression-like behaviors." (PMID 35643536, 2022). "Further, we examined whether depressive phenotype of Ahi1 KO mice is improved by imipramine, a clinical wildly used medication for major depression." (PMID 24691070, 2014). "Therefore, Ahi1 KO mice are a good genetic model of depression for pathologically mechanistic study." (PMID 24691070, 2014). "In addition, Ahi-1 is also found to be abundant in the hypothalamus and amygdala, two important brain region whose dysfunction can lead to emotional and depression phenotypes." (PMID 22248740, 2011). "Sex differences in brain estrogen levels may at least partially account for the differences in depressive behaviors between male and female Ahi1 KO mice, indicating that Ahi1 regulates serotonin production by the GR/ERβ/TPH2 pathway involving sexual differences in depression-like behaviors." (PMID 35643536, 2022). "Therefore, Ahi1 regulates serotonin production by the GR/ERβ/TPH2 pathway involving sex differences in depression-like behaviors; our findings may facilitate finding personalized treatments for patients with MDD." (PMID 35643536, 2022). "Therefore, Ahi1 could be a therapeutic target for the treatment of stress-mediated depressive disorders." (PMID 33782379, 2021). "Therefore, the reduction of AHI1 ultimately results in the downregulation of Tyk2 and subsequent attenuation of IFN-I signaling activity in macrophages obtained from depression." (PMID 38916735, 2024). "In addition, exercise significantly increased mitochondrial Ahi1/GR levels and ATP levels, resulting in the improvement of depression-like behaviors in Dex-induced depressive mice under stress; however, depression-like behaviors and ATP levels were not improved in Ahi1 KO mice under stress." (PMID 36691038, 2023). "The protein levels of 5-HT transporter SERT and the ERα were not changed in male Ahi1 KO and the mouse model of chronic restraint stress-induced depression-like behaviors; therefore, they may not be responsible for the decline in 5-HT levels and depression-like behavior in depressed mice." (PMID 35643536, 2022).
depression (continued). "However, there was no change in the ERβ/TPH2/5-HT pathway or depression-like behavior in female Ahi1 KO and chronic restraint stressed mice, implying that there may be other signaling pathways involved in the regulation of 5-HT and behavior in female Ahi1 KO and chronic restraint stress mice." (PMID 35643536, 2022).
schizophrenia (12 papers, 2010 to 2024). A major psychotic disorder characterized by abnormalities in the perception or expression of reality. "The AHI1 genetic variability was also previously associated with stress response, schizophrenia (SCZ) and mood disorders." (PMID 38036661, 2024). "The Abelson helper integration site 1 (Ahi1) gene plays a pivotal role in brain development and is associated with genetic susceptibility to schizophrenia, and other neuropsychiatric disorders." (PMID 29967406, 2018). "LINC00271 is in a region of high LD with the immediately adjacent gene AHI1, a gene involved in neurodevelopment and implicated in schizophrenia." (PMID 25384046, 2014). "This led to identification of AHI1 as schizophrenia susceptibility gene which was further replicated in an Icelandic case control sample and recently in a large European and Spanish/German samples." (PMID 22247771, 2012). "Single alleles and haplotypes of the AHI1 region associated with schizophrenia in the present study." (PMID 20805890, 2010). "To further investigate the contribution of AHI1 to the susceptibility of schizophrenia, we evaluated the effect of AHI1 variation on the vulnerability to psychosis in two samples from Spain and Germany." (PMID 20805890, 2010). "Our data support, in agreement with previous reports, an effect of AHI1 variation on the susceptibility to schizophrenia in central and southern European populations." (PMID 20805890, 2010). "Particularly, rs7750586 and rs911507, both located upstream of the AHI1 coding region, were found to be associated with schizophrenia in the analysis of genotypic (p = 0.0033, and 0.031, respectively) and allelic frequencies (p = 0.001 in both cases)." (PMID 20805890, 2010). "Taken together, AHI1 is an attractive candidate for a schizophrenia susceptibility gene and three association studies have been performed with promising results." (PMID 20805890, 2010). "According to these antecedents, we performed the present study, which intends to extend the study of AHI1 gene to other populations in an attempt to find schizophrenia-associating markers in the Caucasian European context." (PMID 20805890, 2010). "For example, AHI1 is associated with both schizophrenia and metabolic abnormalities of muscles and perhaps could contribute to these two disease predispositions." (PMID 31615985, 2019). "The present study aimed to explore whether four single nucleotide polymorphisms (SNPs) within the AHI1 gene could be associated with schizophrenia (SCZ) and whether they could predict the clinical outcomes in SCZ patients treated with antipsychotics." (PMID 25622261, 2015). "Our main aim was to test the hypothesis that AHI1 variants were associated with schizophrenia as well as dimensional measures of disease severity." (PMID 20805890, 2010). "Finally, as a complement to our case-control association study, we evaluated the impact on several clinical variables (PANSS, BPRS and KGV scales) of those AHI1 SNPs associated with schizophrenia in this study." (PMID 20805890, 2010). "Here we present the results for a case-control association analysis that explores the impact of variation at AHI1 locus on the vulnerability towards schizophrenia in two European samples of Caucasian origin from Southern Germany and East Spain." (PMID 20805890, 2010). "While the accelerated evolution of AHI1 in the human lineage indicates a role in cognitive (dys)function, a linkage scan in large pedigrees identified AHI1 as a positional candidate for schizophrenia." (PMID 20805890, 2010). "These neural mechanisms may provide initial clues as to the role Ahi1 in schizophrenia and other neuropsychiatric disorders." (PMID 29967406, 2018). "Moreover, a possible link between an AHI1 SNP and a clinical outcome in patients with schizophrenia was found." (PMID 28125008, 2017). "Both studies also supported the hypothesis that AHI1 is involved in the pathogenesis of schizophrenia." (PMID 20805890, 2010).
schizophrenia (continued). "Notwithstanding our finding of association with schizophrenia, we did not observe differences between Ahi1+/+ and Ahi1+/− mice on paradigms that focus on what are considered as rodent-equivalent of positive symptoms such as prepulse inhibition (PPI) or MK-801-induced hyperlocomotion." (PMID 29967406, 2018). "However, although PCM-1 and AHI1 are associated with schizophrenia, there are no observations of implication of either Plk1 or Rab8, into pathogenesis of schizophrenia." (PMID 28125008, 2017).
retinal degeneration (11 papers, 2010 to 2024). Degeneration of the retina. "To determine if heterozygous mutations in other cilia genes could exacerbate retinal degeneration, we bred cep290fh297/fh297 mutants to arl13b, ahi1, and cc2d2a mutant zebrafish lines." (PMID 30970040, 2019). "A previous study showed that removal of one allele of Ahi1, which encodes a component of the ciliary gate complex, significantly increases RHO mislocalization and accelerates retinal degeneration in Nphp1gt/gt mice." (PMID 33961633, 2021). "In this study, we evaluated the zebrafish cep290fh297/fh297 mutant in an effort to test ahi1, cc2d2a, and arl13b as potential genetic modifiers of retinal degeneration." (PMID 30970040, 2019). "Mutations in AHI1 and CEP290, genes critical to primary cilia function, have been linked to retinal degeneration." (PMID 30518138, 2018). "Ahi1−/− mutant mice fail to develop photoreceptor outer segments, leading to retinal degeneration." (PMID 23028714, 2012). "More recently, it has been reported that mutations in Abelson helper integration site 1 protein homolog (AHI1), which interacts with NPHP1, act as modifier of retinal degeneration phenotype in nephronophthisis." (PMID 20664800, 2010). "Strikingly, one of the AHI1 variants they described as a potential modifier for neurological involvement in patients with NPHP1 mutations, p.Arg830Trp, was recently identified as a modifier allele for retinal degeneration in patients with NPHP, independent of a primary NPHP1 mutation." (PMID 20683928, 2010).
leukemia (10 papers, 2011 to 2023). A malignant (clonal) hematologic disorder, involving hematopoietic stem cells and characterized by the presence of primitive or atypical myeloid or lymphoid cells in the bone marrow and the blood. "Moreover, intravenous injection of NOD/SCID-beta2m immunodeficient mice with either Ahi-1- or BCR-ABL-transduced BaF3 cells causes lethal leukemia within 70 and 40 days, respectively." (PMID 22248740, 2011). "The Abelson helper integration site-1 (AHI1) locus was initially identified as a common helper provirus integration site for murine leukemias and lymphomas." (PMID 30949029, 2019). "Ahi-1 (Abelson helper integration site 1) is a novel oncogene commonly activated by provirus insertional mutagenesis in v-abl and myc-induced murine leukemias and lymphomas." (PMID 22248740, 2011). "The oncogenic role of AHI1 has been identified in human leukemia and Sezary syndrome." (PMID 34950701, 2021). "Therefore, alterations in AHI1 expression may contribute to the development of certain types of human leukemias." (PMID 37547536, 2023). "The first evidence that AHI-1 may be involved in the regulation of human leukemia and lymphoma development is based on an interesting observation that AHI-1 transcripts are significantly higher in a broad spectrum of established human leukemic and lymphoid cell lines, compared to normal human BM." (PMID 22248740, 2011). "Interestingly, overexpression of Ahi-1 alone in primitive hematopoietic cells confers a proliferative advantage in vitro and induces a lethal leukemia in vivo; these effects can be enhanced by BCR-ABL, a fusion oncoprotein that plays a major role in the genesis of CML." (PMID 22248740, 2011). "Abelson helper integration site-1 (AHI1) is an oncogene and has an oncogenic effect on the development of human leukemia." (PMID 33996564, 2021). "One promising candidate as a potential therapeutic target is Abelson helper integration site-1(Ahi-1/AHI-1) that was identified by retroviral insertional mutagenesis in murine models of leukemia/lymphomas and is highly elevated in certain human lymphoma and leukemia stem/progenitor cells." (PMID 22248740, 2011).
nephronophthisis (9 papers, 2010 to 2024). Progressive tubulointerstitial injury, inherited in an autosomal recessive pattern, caused by mutations in genes involved in ciliary function, which may result in an end stage renal failure. "One study has demonstrated the development of the cystic kidney disease nephronophthisis as a potential cause of death in Ahi-1-null mice." (PMID 22248740, 2011). "In another study, the same hypomorphic variant in AHI1 was associated with retinal disease in 153 patients with nephronophthisis irrespective of the underlying genetic cause of nephronophthisis." (PMID 37628633, 2023).
lymphoma (7 papers, 2011 to 2021). A malignant (clonal) proliferation of B- lymphocytes or T- lymphocytes which involves the lymph nodes, bone marrow and/or extranodal sites. "The Ahi-1 (Abelson helper integration site-1) locus was initially identified as a common helper provirus integration site in 16% of Abelson murine leukemia virus (A-MuLV)-induced pre-B lymphomas." (PMID 22248740, 2011).
Retinal dystrophy (6 papers, 2015 to 2022). Retinal dystrophy is an abnormality of the retina associated with a hereditary process. "Pathological variants responsible for JBTS associated with retinal dystrophies involve AHI1 in 4 families, followed by CEP290 and INPP5E in 2 families each, and NPHP1 in one family." (PMID 35551639, 2022). "On the other hand, individuals with causal variants in the CEP290 or AHI1 need a closer surveillance for retinal dystrophy and, in case of CEP290, also for chronic kidney disease." (PMID 35238134, 2022). "The gene most commonly observed to cause retinal dystrophy is AHI1, followed by INPP5E, but a total of 14 genes have been reported to be responsible for this phenotype." (PMID 30518138, 2018). "Patients with JS with ocular defects (JS-O) suffer from retinal dystrophy that varies in progression and severity in addition to the abnormalities of the classic form; AHI1 mutations are frequent in this subgroup." (PMID 30518138, 2018). "Almost 80 % of patients with AHI1 mutations have retinal dystrophy and early onset congenital blindness." (PMID 26541515, 2015). "A specific association of retinal dystrophy with macular staphyloma has also been reported in few patients with AHI1‐ and INPP5E‐related JS, while the “morning glory disc anomaly” has been observed in an Austrian family with biallelic TMEM237 pathogenic variants." (PMID 35238134, 2022). "CEP290 is the most frequent JBTS causative gene, but variants in AHI1 and INPP5E are the most frequently associated to retinal dystrophies." (PMID 35551639, 2022).